MYH10 (myosin heavy chain 10)
Diseases named in the same sentence as MYH10 in open-access papers (continued):
Sharing a sentence is not in itself a finding about the gene and the disease.
epilepsy (1 paper, 2020). A brain disorder characterized by episodes of abnormally increased neuronal discharge resulting in transient episodes of sensory or motor neurological dysfunction, or psychic dysfunction. "We hypothesize that the upregulation of NMDAR interactors, such as Dlg3, Myh10, Ppp3a, Psen1, and Dnm1, may contribute to the anti-epilepsy phenotype by keeping the activity of NMDARs in control." (PMID 32033586, 2020).
gastric cancer (1 paper, 2025). A primary or metastatic malignant neoplasm involving the stomach. "Meanwhile, the AC107021.2/MYH10 signaling axis influences the prognosis of gastric cancer via the TIGHT JUNCTION, VIRAL MYOCARDITIS, and REGULATION OF ACTIN CYTOSKELETON signaling pathways." (PMID 40104507, 2025).
glomerular disease (1 paper, 2009). "By contrast, another of our highly enriched mRNAs, that encoding myosin IIb (Myh10) has been shown to be overexpressed in a number of glomerular disease models." (PMID 19652713, 2009).
hearing loss (1 paper, 2025). "In some case reports, MYH14 mutations in patients are associated with hearing loss and MYH10 mutations with microcephaly, developmental delay, hydrocephalus, cerebral and cerebellar atrophy, and hearing loss." (PMID 40464565, 2025). "There is still no conditional mouse model study utilizing outer hair cell (OHC)–specific Cre, such as Prestin-CreERT2+/−, to investigate the role of MYH9 or MYH10 in hearing loss." (PMID 40464565, 2025).
Hypernatremia (1 paper, 2025). An abnormally increased sodium concentration in the blood. "While male Myh9/Myh10 TAL-cKO developed polyuria and polydipsia concurrently with hypernatremia, females exhibited an earlier onset of hypernatremia in the absence of these findings." (PMID 39986266, 2025).
hypertrophic cardiomyopathy (1 paper, 2024). A condition in which the myocardium is hypertrophied without an obvious cause. "This study revealed the potential relationship between disulfidptosis and hypertrophic cardiomyopathy and put forward a predictive model containing disulfidptosis-associated genes (DRGs) of GYS1, MYH10, PDMIL1, SLC3A2, CAPZB, showing excellent performance by SVM machine learning model." (PMID 39701955, 2024).
lymph-node metastasis (1 paper, 2025). "The same study identified genes associated with lymph-node metastasis and MYH10 was not listed." (PMID 40164920, 2025).
malaria (1 paper, 2022). Malaria is a serious and sometimes fatal disease caused by a parasite that commonly infects a certain type of mosquito which feeds on humans. "In the liver, Myh10, Tubb1, and Notch4 were constitutively expressed and their expression responded to both blood-stage malaria and vaccination." (PMID 35214745, 2022). "The constitutive expression of Myh10, approximately 51, resembled that of Notch4, but its response to malaria and vaccination was totally different from that of Notch4." (PMID 35214745, 2022).
male infertility (1 paper, 2025). The inability of the male to effect fertilization of an ovum after a specified period of unprotected intercourse. "Together, our findings establish CFAP57 as an important mediator of sperm flagellogenesis that orchestrates MYH10 and IFT88 positioning and intraflagellar transport dynamics to maintain flagellar integrity, providing molecular insights into MMAF-associated male infertility." (PMID 41466333, 2025). "Collectively, these findings not only clarify the role of CFAP57 in MMAF pathogenesis but also reveal a previously unrecognized function of MYH10 in sperm flagellogenesis, providing new insights into the molecular etiology of male infertility and highlighting potential therapeutic targets." (PMID 41466333, 2025). "IFT88, a key component of the IFT-B complex, plays a crucial role in the assembly of mouse sperm flagella, as its absence leads to defects in flagellar structure and male infertility In this study, Our IF and IEM analysis confirmed MYH10 pan-axonemal localization in sperm tail." (PMID 41466333, 2025).
May-Hegglin anomaly (1 paper, 2022). "Mutations in MYH10 (Myosin Heavy Chain 10) have been associated with May-Hegglin anomaly and developmental defects in brain and heart." (PMID 35309948, 2022).
myeloma (1 paper, 2023). "We selected genes (ARHGAP26, MYH10, PMP2, RFX8, BAMBI, CLEC12b) with significant changes in methylation level to validate their expression using qRT-PCR in U266 myeloma cells." (PMID 38201971, 2023).
myocardial infarction (1 paper, 2013). Gross necrosis of the myocardium, as a result of interruption of the blood supply to the area, as in coronary thrombosis. "After myocardial infarction, MYH10 expression is upregulated in myofibroblasts during the early stages of cardiac remodeling." (PMID 22565821, 2013). "Only indirect links exist between MYH10 expression and disease processes, such as scar tissue formation following myocardial infarction, demyelination, and the inherited neurodegenerative disease, juvenile-onset neuronal ceroid lipofuscinosis (JNCL)." (PMID 22565821, 2013).
ptosis (1 paper, 2024). The drooping of the upper eyelid. "We identified heterozygous MYH10 variants in five pedigrees with CN3-oCCDDs: ENG_CKM (isolated familial CFEOM), ENG_ASW (syndromic sporadic CFEOM), ENG_YY (isolated sporadic MGJWS(+)ptosis), ENG_PJ (isolated sporadic MGJWS(+)ptosis), and ENG_CGO (isolated sporadic MGJWS(−)ptosis)." (PMID 38585811, 2024).
serous carcinoma (1 paper, 2024). "This patient’s tumor represents a high grade serous carcinoma harboring a previously unreported NRG1 fusion; the gene is spliced with MYH10 with an exon 2 breakpoint." (PMID 39575425, 2024).
viral myocarditis (1 paper, 2019). Myocarditis that is caused by an infection with a viral agent. "The viral myocarditis pathway was the only significantly enriched pathway that was distinct to SF; with associated genes falling in the myosin family (Myh2, Myh3, Myh10 and Myh7b)." (PMID 31253821, 2019).
tumor (23 papers, 2015 to 2025). "Consistent with its recurrent copy number loss and down‐regulation in HCC tissues, MYH10 plays a tumour‐suppressive role in HCC by reducing HCC metastasis both in vitro and in vivo." (PMID 34738311, 2021). "This is consistent with previous reports that both MYH9 and MYH10 are overexpressed in several tumors and linked to bad prognosis of these tumor patients." (PMID 29439719, 2018). "In A549, MCF7, and MHCC-97H cells, silencing either MYH9 or MYH10 significantly increased ROS production, reduced mitochondrial membrane potential, and inhibited clonal formation and tumor cell viability." (PMID 37891404, 2024). "MYH9 and MYH10 silencing were also shown to reverse the proliferative effects of LAMC2 overexpression on tumor cells." (PMID 37891404, 2024). "The study also observed an increase in the methylation levels of genes (NTN1, MYH10) involved in tumor development, progression, proliferation, and migration." (PMID 38201971, 2023). "Linear regressions were performed to evaluate the ability of tumor burden (as % of body mass) to predict MYH10, TGBI, CTGF, and C5 relative abundance values." (PMID 35422813, 2022). "The models estimate CTGF, TGFBI, and MYH10 abundances enhance 1.95, 0.54- and 1.13-fold, respectively, for each 1% increase in tumor burden." (PMID 35422813, 2022). "Our findings highlighted that MYH10 is a novel tumour suppressor of HCC, providing an important supplement to the mechanism of HCC development and metastasis." (PMID 34738311, 2021). "Here, utilizing an integrative omics analysis, we screened out a novel tumour suppressor gene within 17p13.1, myosin heavy chain 10 (MYH10)." (PMID 34738311, 2021). "In the present study, we clarified a novel candidate tumour suppressor gene MYH10 driven by 17p13.1 deletions in HCC through an integrative omics analysis." (PMID 34738311, 2021). "In this study, utilizing an integrative omics analysis in HCC, we screened out MYH10 as a novel tumour suppressor within the genomic deletion region at chromosome 17p13.1." (PMID 34738311, 2021). "In conclusion, the survey revealed that, for the first time, MYH10 functions as a promising tumour suppressor driven by copy number deletion at 17p13.1 in the development of HCC." (PMID 34738311, 2021). "Here, we prioritized a novel candidate tumour suppressor gene MYH10 within this depleted region through an integrative omics analysis." (PMID 34738311, 2021). "Current tumor studies related to MYH10 have shown that MYH10 plays different roles in different tumors." (PMID 32226520, 2020). "In the Okayama Lung dataset, the alternation of ADAMTS8, METTL7A, MYH10 and PRC1 were associated with tumor grade, implicating vital roles of these genes in the carcinogenesis or progression of LUAD." (PMID 31333911, 2019). "In conclusion, our study suggests that MYH10, a candidate target gene for 17p13 deletion, acts as a tumour suppressor and may serve as a potential prognostic indicator for HCC patients." (PMID 34738311, 2021). "Taken together, these data suggested that inhibition of EGFR pathway activation may be responsible for the tumour‐suppressive effect of MYH10." (PMID 34738311, 2021). "These discordances might be due to tumour heterogeneity that MYH10 exerts its role in a context‐dependent manner." (PMID 34738311, 2021). "MYH9 and MYH10 mutations were identified at a similar frequency in 4–5% of cases, and MYH14 was mutated in 2 tumors, and these mutations tended to be mutually exclusive except in one tumor where co-occurrence of MYH9 and 10 mutations was observed." (PMID 26369831, 2015). "Therefore, we hypothesized that MYH10 exerts its tumour‐suppressive role by reducing the activation of EGFR pathway." (PMID 34738311, 2021). "However, it lacks evidence for MYH10’s tumour‐suppressive role in HCC progression." (PMID 34738311, 2021).
tumor (continued). "In order to clarify the relationship between DRP1 and LAMC2/MYH9/MYH10 complexes, the DRP1 inhibitor Mdivi-1 and Mdivi-1+Tun were used to treat tumor cells." (PMID 37891404, 2024). "The results demonstrated that all 27 disulfrgs, except for NDUFS1, NUBPL, MYH10, and IQGAP1 genes, exhibited significantly higher expression in tumor tissues." (PMID 38831301, 2024). "In order to prove that ER stress promotes the formation of LAMC2/MYH9/MYH10 complexes, tunicamycin was used to treat tumor cells, and the results showed that the expression of LAMC2, MYH9, MYH10, GRP78 and DRP1 was significantly increased." (PMID 37891404, 2024). "Percent tumor burden explained a modest amount of variation in abundance of both CTGF and TGFBI (R2 = 0.18) and slightly less for MYH10 (R2 = 0.16)." (PMID 35422813, 2022). "Percent tumor burden was a significant predictor of CTGF (F = 9.55, p < 0.01), TGFBI (F = 9.41, p < 0.01), and MYH10 abundance (F = 7.96, p < 0.01)." (PMID 35422813, 2022). "After MWA, tumor-promoting genes such as BCL3, Myh10, NR6A1, and PFKFB3 displayed downregulation." (PMID 38779358, 2024). "Myosin heavy chain 10 (MYH10), transforming growth factor beta induced (TGFBI) and CTGF were the proteins that correlated best with tumor volume, and their expression levels enhanced as tumor volume increases." (PMID 35422813, 2022). "The results showed that knockdown of MYH10 does not affect the tumour growth and tumour weight, indicating that MYH10 is not required for in vivo tumorigenicity." (PMID 34738311, 2021). "Again, HCC tumours with MYH10 deletions also presented lower expression levels of MYH10 compared to those without MYH10 deletions (p = 0.0001)." (PMID 34738311, 2021). "Notably, it was shown that MYH10 is consistently down‐regulated (p < 0.05, log2[fold‐change] <−0.2) in HCC tissues compared to adjacent non‐tumour liver tissues (ANTLs) in 11 out of the 12 datasets, increasing its candidacy as the functional target within this deleted region." (PMID 34738311, 2021). "Taken together, our single-cell RNA expression analysis affirmed that SELPLG and SH2D2A are differentially regulated in single tumor-infiltrating L1CAM-CAR T cells, suggesting a functional role, while TIAM2, CORO1B and MYH10 do not seem to influence L1CAM-CAR T cell migration." (PMID 41394860, 2025).
cancer (17 papers, 2015 to 2025). A tumor composed of atypical neoplastic, often pleomorphic cells that invade other tissues. "Moreover, MYH10, a member of the protein-coding gene superfamily, not only participates in normal cellular physiological activities but also bears close association with cancer initiation and progression." (PMID 38836761, 2024). "A recent study revealed that UCEC is one of the two cancer types with the highest mutation rates in disulfidptosis-related genes, whereas mutations in the ACTN4 and MYH10 genes are closely linked to poor survival." (PMID 39931061, 2025). "The specific effects of SR1848, which inhibits NR5A2, ON1231320 or BI2536, which inhibits PLK2, and blebbistatin, which inhibits MYH10, were further validated in cancer cell lines." (PMID 39814695, 2025). "Further, we analysed the prevalence of MYH10 deletion in 33 types of cancer from TCGA and found that the frequency of MYH10 deletion was greater than 30% in half of the cancer types." (PMID 34738311, 2021). "Further studies are warranted to explore the functional consequence of MYH10 in different types of cancer." (PMID 34738311, 2021). "Our results also indicated that MYH10 deletion is a trans‐cancer genomic feature and deserves more attention on its biological and clinical relevance in multi types of cancer." (PMID 34738311, 2021). "In present study, we found in 48 NPC specimens, MYH10 level was lower in most cancer areas than that in the adjacent normal tissue." (PMID 32226520, 2020). "In 2 cases, MYH10 index was higher than normal tissues, accounting for 4.17% In other 9 samples, the positive index of cancer tissue and normal tissue was equal, accounting for 18.75%." (PMID 32226520, 2020). "More intensive efforts will be required to elucidate the relationship between BMP4 and MYH10 and to clarify the roles of MYH10 in cancer progression." (PMID 26395571, 2015). "In addition, we showed that MYH9 and MYH10 knockdown cancer cells exhibited lower colony formation and cell viability compared to the control group cells." (PMID 37891404, 2024). "Moreover, the expression levels of MYH10 are significantly correlated with the copy numbers in these types of cancer, suggesting MYH10 deletion as a trans‐cancer genomic feature." (PMID 34738311, 2021). "These experimental results all indicated that MYH10 had an anti-cancer effect." (PMID 32226520, 2020). "To examine the effect of LAMC2 on MYH9 and MYH10, we performed western blotting analyses using si-LAMC2 cancer cells, and showed that silencing LAMC2 significantly reduced the protein levels of MYH9, MYH10, as well as DRP1 and phosphorylated DRP1." (PMID 37891404, 2024). "Taken together, this study proposes that in mitigating ER stress in cancer cells, LAMC2 exerts an emergency stress-resistance response by binding to MYH9 and MYH10 to promote ER-mitochondria interaction around the nucleus." (PMID 37891404, 2024). "Most signaling pathways in pan-cancer, including ACTB, FLNA, MYH9, MYH10, and TLN1, exhibited high activation levels in the epithelial-mesenchymal transition (EMT) pathway, but consistent inhibition of the cell cycle, DNA damage response, and hormone AR." (PMID 38862242, 2024). "Taken together, our results revealed that in complex with MYH9 and MYH10, LAMC2 is essential for promoting ER-mitochondria interaction to alleviate ER stress and allow cancer cells to adapt and proliferate under stressful conditions." (PMID 37891404, 2024). "MHY9, INF2, FLNA, MYH10, FLNB, FLN1, and ACTB were upregulated in HNSC cancer tissues." (PMID 38584831, 2024). "Therefore, we would like to focus our discussion on genes that have been reported in cancer research, such as ESRP2, MUC17, MYH10, and SSX2IP." (PMID 38893126, 2024).
cancer (continued). "From the differential genes involved in these pathways, we identified several gene clusters uniquely upregulated in the CAFWPOI 4-5 type; neuronal development and function-related (RELN, MYH10, CACNB4, OXTR, CAV3, CHRM2) and inflammation and cancer-related (RELN, IL21R, EDNRB, CAV3, OXTR)." (PMID 36045118, 2022).
kidney disease (3 papers, 2020 to 2025). "Our experiments show that conditional genetic inactivation of Myh9 and Myh10 in the TAL segment results in progressive kidney disease." (PMID 39500539, 2025). "Inducible conditional knockout (cKO) of Myh9 and Myh10 in the renal tubules of adult mice resulted in progressive kidney disease." (PMID 33001861, 2020). "Adult mouse renal epithelium specific knockout of Myh9 and Myh10 genes result in kidney disease." (PMID 33001861, 2020). "Perspectives regarding the mechanism and treatment of APOL1-related kidney disease are discussed, as well as speculations on additional APOLs functions, such as APOL6 involvement in adipocyte membrane dynamics through interaction with myosin-10 (MYH10)." (PMID 38478101, 2024).
neurodevelopmental disorder (2 papers, 2024 to 2025). A behavioral and cognitive disorder with onset during the developmental period that involves impaired or aberrant development of intellectual, motor, or social functions. "While MYH10 has not been linked to MMAF in humans, recent studies show heterozygous MYH10 variants cause neurodevelopmental disorders and congenital anomalies, indicating its critical role in primary cilia formation." (PMID 41466333, 2025).
bacterial infection (1 paper, 2020). "Functional annotation of putatively selected genes revealed that these genes were predominantly associated with immune-related functions, inclusive of genes such as C5AR1 and MYH10 (bacterial infection); ARHGEF1, ERCC2 and TRAF2 (viral infection) and IFNGR2 (both viral and bacterial infection)." (PMID 33116287, 2020).
MYH10 also shares sentences with these, for which no sentence is quoted: infection (3 papers); atherosclerosis (2); diaphragmatic hernia (2); prostate carcinoma (2); viral infection (2); alcohol dependence (1); Atrophy (1); autism spectrum disorder (1); cardiac hypertrophy (1); Cerebellar atrophy (1); coloboma (1); colon cancer (1); congenital diaphragmatic hernia (1); congestive heart failure (1); Cyanosis (1); developmental delay (1); dilated cardiomyopathy (1); fungal infection (1); genetic disorders (1); human papillomavirus infection (1); idiopathic cardiomyopathy (1); infertile (1); ischemic cardiomyopathy (1); leiomyoma (1); lung squamous cell carcinoma (1); mesenchymal tumors (1); metastatic disease (1); Obesity (1); omphalocele (1); ovarian carcinoma (1).
A further 8 diseases each share a sentence with MYH10 in 1 paper.